RBP2 (retinol binding protein 2)
Diseases named in the same sentence as RBP2 in open-access papers (continued):
Sharing a sentence is not in itself a finding about the gene and the disease.
Glucose intolerance (1 paper, 2021). Glucose intolerance (GI) can be defined as dysglycemia that comprises both prediabetes and diabetes. "Thus, obesity, glucose intolerance, and fatty liver phenotypes documented in Rbp2−/− mice might arise as a consequence of an increased concentration of 2-AG and other bioactive MAGs." (PMID 33631211, 2021).
ischemia (1 paper, 2017). A hypoperfusion of the BLOOD through an organ or tissue caused by a PATHOLOGIC CONSTRICTION or obstruction of its BLOOD VESSELS, or an absence of BLOOD CIRCULATION. "Postischemia administration of 2.7 g/Kg/day XFZYD also significantly [I/R + XFZYD2.7 (VEGF = 1.90 ± 0.34; HIF-1α = 1.87 ± 0.22; PKM2 = 5.86 ± 0.95, p < 0.001; RBP2 = 5.19 ± 1.17, p = 0.008)] mitigated this ischemia-induced increase." (PMID 28709426, 2017). "Postischemia administration of 2.7 g/Kg/day XFZYD also significantly (I/R + XFZYD2.7: VEGF = 2.91 ± 1.59, p = 0.029; HIF-1α = 1.57 ± 0.61, p = 0.006; PKM2 = 2.62 ± 0.49, p = 0.002; RBP2 = 1.42 ± 0.52, p = 0.005) attenuated this ischemia-induced increase." (PMID 28709426, 2017).
liver cancer (1 paper, 2016). An epithelial or non-epithelial malignant neoplasm that arises from the liver. "Lysine demethylase 5A (KDM5A/RBP2/JARID1A) is a histone lysine demethylase that is overexpressed in several human cancers including lung, gastric, breast and liver cancers." (PMID 27224921, 2016).
malaria (1 paper, 2015). Malaria is a serious and sometimes fatal disease caused by a parasite that commonly infects a certain type of mosquito which feeds on humans. "Through the use of our novel rbp2 qPCR assay, we aim to characterize the prevalence of P. ovale in future epidemiological studies in order to better understand this neglected malaria parasite species." (PMID 25590587, 2015). "Our study was also limited by only testing samples collected in Western Kenya and additional validation is therefore needed to confirm the ability of the rbp2 qPCR assay to detect total P. ovale from other malaria endemic regions." (PMID 25590587, 2015). "We used the rbp2 plasmid to determine the linear dynamic range and limit of detection because of difficulties obtaining pure P. ovale infected samples from malaria endemic regions and the inability to culture P. ovale parasites." (PMID 25590587, 2015). "P. ovale parasitemias are characteristically lower than other malaria species, so we limited the testing of our upper dynamic range to 100,000 rbp2 copies per microliter, as higher copy numbers would likely be epidemiologically and clinically irrelevant." (PMID 25590587, 2015). "Specificity experiments showed the ability of the rbp2 qPCR assay to detect low-levels of P. ovale in the presence of additional malaria parasite species, including P. falciparum, P. vivax, and P. malariae." (PMID 25590587, 2015). "We tested DNA from P. knowlesi, P. fragile, and P. cynomolgi and found DNA from these malaria parasite species were undetectable by our rbp2 qPCR assay." (PMID 25590587, 2015). "Our novel P. ovale rbp2 qPCR assay detects P. ovale curtisi and P. ovale wallikeri simultaneously and can be utilized to characterize the prevalence, distribution, and burden of P. ovale in malaria endemic regions." (PMID 25590587, 2015). "Our P. ovale-specific rbp2 qPCR assay can be utilized to better characterize the presence, parasitemia, geographical distribution, and the contribution of P. ovale to mixed-species infections and to clinical disease in malaria endemic regions." (PMID 25590587, 2015). "Our new inclusive P. ovale-specific qPCR assay is based on rbp2, a gene that contains conserved regions between P. ovale curtisi and P. ovale wallikeri but that is absent from other human malaria parasite species." (PMID 25590587, 2015).
metastatic tumors (1 paper, 2016). "The observation of significantly increased levels of RBP2 in liver metastases suggests a role for RBP2 in the metastatic tumors." (PMID 27548814, 2016).
myeloid leukemia (1 paper, 2016). A clonal proliferation of myeloid cells and their precursors in the bone marrow, peripheral blood, and spleen. "Remarkably, RBP2 plays contrasting roles in ALL and myeloid leukemia." (PMID 27008505, 2016).
myocardial infarction (1 paper, 2022). Gross necrosis of the myocardium, as a result of interruption of the blood supply to the area, as in coronary thrombosis. "LncRNA Tsix was found to specifically bind mir-34a-5p, which relieves the inhibition of retinol binding protein 2 expression by the latter, plays a role in anti-cardiomyocyte apoptosis and improves cardiac function injury after myocardial infarction." (PMID 35094641, 2022).
osteoporosis (1 paper, 2021). A condition of reduced bone mass, with decreased cortical thickness and a decrease in the number and size of the trabeculae of cancellous bone (but normal chemical composition), resulting in increased fracture incidence. "In another study of the underlying molecular mechanisms of osteoporosis, RBP2 was shown to be upregulated during osteoporosis." (PMID 33941771, 2021).
pancreatic NET (1 paper, 2016). "Conversely, to further understand the role of RPB2 in NET formation, we transiently knocked down RBP2 in the NET cell lines H727 (derived from lung carcinoid NET) and QGP-1 (derived from somatostatinoma pancreatic NET), which both have high levels of RBP2." (PMID 27548814, 2016).
parasitemia (1 paper, 2015). "The lower, non-linear but still clearly positive limit of detection of our assay was determined to be 1.5 copies of rbp2 per microliter, confirming this assay’s capacity to detect low-level parasitemias." (PMID 25590587, 2015). "Quantitative parasitemia determined by expert microscopy (parasites per microliter) was compared to the rbp2 copy number per microliter based on the rbp2 plasmid standard curve." (PMID 25590587, 2015). "As the 22 samples included in this study were identified as P. ovale by microscopy, further studies are needed to test the P. ovale rbp2 qPCR assay with submicroscopic and asymptomatic P. ovale infections with a range of parasitemias." (PMID 25590587, 2015). "Variation between parasitemia and rbp2 copy number could also be explained by the P. ovale parasite stage." (PMID 25590587, 2015). "The limited correlation between microscopy and rbp2 qPCR results is not surprising as parasitemia calculations for P. ovale human samples at low parasitemias are notoriously difficult, particularly in co-infected samples." (PMID 25590587, 2015).
prostate carcinoma (1 paper, 2011). A carcinoma that arises from epithelial cells of the prostate gland. "The fact that RBP2 interacts with nuclear receptors and enhances expression of their target genes suggests that RBP2 could recruit additional factors important for nuclear receptor-mediated transcription, which plays important roles in breast and prostate cancer progression." (PMID 21544224, 2011).
retinal ischemia (1 paper, 2017). A ischemic disease that involves the retina. "Presently, JIB-04, a paninhibitor of the Jumonji demethylase superfamily, was thus selected to observe the inhibition of RBP2 upregulation in retinal ischemia." (PMID 28709426, 2017). "The enhanced mRNA/protein concentrations of RBP2 and PKM2, as well as the consequential stimulation of HIF-1α and VEGF mRNA/protein levels as measured during the present investigation are clearly associated with retinal ischemia and, possibly, wAMD." (PMID 28709426, 2017). "When our findings are taken as a whole, XFZYD would seem to have a preventive or protective effect on retinal ischemia via the downregulation of HIF-1α expression and a reduction in VEGF secretion; this ocurrs via an inhibition of RBP2 and PKM2." (PMID 28709426, 2017).
cancer (21 papers, 2011 to 2025). A tumor composed of atypical neoplastic, often pleomorphic cells that invade other tissues. "We are now focusing on RBP2, the newly identified histone demethylase, which is closely associated with cancer development and progression." (PMID 25974964, 2015). "Others found that loss of the retinoblastoma binding protein 2 (RBP2) histone demethylase suppresses tumorigenesis in mice lacking Rb1 or Men1 and Sharma SV published data illustrating a chromatin-mediated reversible drug-tolerant state in cancer cell subpopulations." (PMID 25015565, 2014). "Moreover, loss of RBP2 dramatically inhibits tumorigenesis in a mouse cancer model." (PMID 21544224, 2011). "CCNA2, SFN, HMGA2, SOX2, and RBP2 have been identified as significant biomarkers for cancer diagnosis and prognosis, particularly in liver cancer." (PMID 40251374, 2025). "In the cellular lipid metabolism process, Bacteroides_sartorii was positively correlated with lipid metabolism-related gene of Mttp, cancer-related genes of Rbp2, and Dhrs9, but was also negatively correlated with cancer-related genes of Neu1 and Hmgcs2." (PMID 39727670, 2025). "Some data have proved that tumor cells often obtain the stem cell property during EMT which is the reason why it is sometimes easy for cancer to relapse, thereby next we tried to determine the role of RBP2 in stem cell property maintenance." (PMID 25974964, 2015). "Immunohistochemical staining of the serial sections of cancer tissues showed that the median MVD was 59.6 in the high RBP2 expression group (7.8 to 102) and 35.4 in the low RBP2 expression group (6.4 to 94)." (PMID 25162518, 2014). "RBP2 serves as an important bridge that links infection (inflammation) to cancer development, which, at least in part, delineates the mechanism for GC development induced by Helicobactor Pylori." (PMID 25015565, 2014). "We detected the critical role of RBP2 in angiogenesis by the biological effect in human cancer cells and animal models." (PMID 24716659, 2014). "RBP2 was identified as a key molecule in drug tolerance of cancer cells and maintaining cancer stem cells." (PMID 24716659, 2014). "Specimens that overexpressed RBP2 accounted for 52.46% of the cancer samples, and most of these samples exhibited intermediate to strong staining." (PMID 24376841, 2013). "To investigate the roles of RBP2 in cancer metastasis, we studied the effect of RBP2 on EMT, as EMT is closely correlated with cancer metastasis." (PMID 24376841, 2013). "A recent study suggested that increased expression of RBP2 promoted a stem cell like phenotype and enhanced resistance to anti-cancer agents by changing chromatin structure." (PMID 21544224, 2011). "Jejunum IEC-Exos contained high levels of RBP2, which could participate in the proliferation, migration, metastasis, and drug resistance of cancer cells." (PMID 35283765, 2022). "RBP2 has been found to actively participate in cancer progression." (PMID 24376841, 2013). "Upregulation of RBP2 was a characteristic of a drug-tolerant cancer cell subpopulation." (PMID 23922798, 2013). "All of these data suggest that RBP2 is an oncogene and provide guidance for cancer treatment." (PMID 24376841, 2013). "As a histone demethylase, RBP2 actively takes part in cancer progression." (PMID 24376841, 2013). "Our research enriches the mechanisms of RBP2-mediated cancer metastasis." (PMID 24376841, 2013). "Cell senescence was induced with RBP2 siRNA knockdown for 72 hr in cancer cells." (PMID 23922798, 2013). "Recently, upregulation of RBP2/KDM5A expression was seen as characteristic of a drug-tolerant cancer cell subpopulation, cancer stem cells, which highlights the role of RBP2 in tumors and suggests its role in the initiation and development of HCC, but its mechanism in cancer was not eluciated." (PMID 23922798, 2013). "Of special interest is the interaction of RBP2 with Myc, which is often activated in cancers." (PMID 21544224, 2011).
cancer (continued). "We investigated the effects of siRNA-mediated depletion of histone demethylase Jarid1A (KDM5A, RBP2), which demethylates transcription activating tri- and dimethylated lysine 4 at histone H3 (H3K4me3/me2), on growth characteristics and cellular response to radiation in several cancer cell lines." (PMID 27253695, 2016). "In addition, RBP-2 promotes cancer cell survival and proliferation." (PMID 24134677, 2014). "Here, we present a new mechanism that RBP2 may play a role in cancer metastasis by inducing EMT." (PMID 24376841, 2013). "RBP2 (retinol binding protein 2), belongs to the Fatty-acid binding protein (FABP) family, was reported to be involved in the pathogenesis of diverse types of cancer." (PMID 32046766, 2020). "In particular, KDM5A (JARID1A/RBP2) and KDM5B (JARID1B/PLU1) contribute to cancer cell proliferation, reduce the expression of tumor suppressor genes, promote the development of drug tolerance and maintain tumor initiating cells." (PMID 31060229, 2019). "Differential expression analysis between GIM and GA showed gene profiles and identified genes that were uniquely expressed in cancer cells, particularly RBP2 expression not in GA but in GIM." (PMID 39496635, 2024). "One such potential target is retinoblastoma-binding protein 2 (RBP2), an H3K4 demethylase whose overexpression has been linked to cancer formation and metastasis in non-endocrine tumor types." (PMID 27548814, 2016). "However, this study did not analyze the effects of RBP2 on E-cadherin, N-cadherin and snail which are important molecules involved in cancer metastasis." (PMID 24376841, 2013).
tumor (16 papers, 2011 to 2025). "Relationships between RBP2 protein expression and clinicopathologic factors were examined by the chi-square test and our data showed that RBP2 overexpression was associated with tumor size (P = 0.030), high HIF-1α expression (P = 0.028) and high VEGF expression (P = 0.048)." (PMID 25162518, 2014). "In addition, high RBP2 expression was closely associated with tumor size, high HIF-1α expression, high VEGF expression and increased tumor angiogenesis." (PMID 25162518, 2014). "RBP2 was significantly elevated at the RNA level in 20 out of 25 human tumor samples compared with matched normal tissue, with an average upregulation greater than threefold." (PMID 27548814, 2016). "Combined with the results presented above, this observation strengthens the idea that modest RBP2 overexpression, as seen in human tumors, contributes to tumor growth and metastasis." (PMID 27548814, 2016). "In conclusion, the results presented here are the first to dissect the role of RBP2 in the development of NETs and to establish that the overexpression seen in patient tissue samples contributes to tumor formation and metastasis." (PMID 27548814, 2016). "Subcutaneous xenografts from βlox5 cells overexpressing RBP2 result in a significant increase in tumor volume (P<0.02) 9 days after subcutaneous injection compared to βlox5 cells containing empty vector." (PMID 27548814, 2016). "Perhaps, the most interesting and unexpected observation was the nearly universal difference in RBP2 localization in well-differentiated versus poorly differentiated neuroendocrine cells in tumor specimens." (PMID 27548814, 2016). "Further, knockdown of RBP2 with siRNAs in H727 cells resulted in a significant decrease in tumor volume (P<0.005) 9 days after injection when compared with cells transfected with scrambled siRNA." (PMID 27548814, 2016). "Immunohistochemistry yielded similar results as RNA analysis, showing an increase in RBP2 protein in neuroendocrine primary tumors and secondary metastatic sites compared with adjacent normal, non-tumor tissue." (PMID 27548814, 2016). "In marked contrast, only 30% and 20% mice had obvious liver and kidney metastasis respectively in RBP2 shRNA group, suggesting that RBP2 inhibition decreased tumor metastasis in vivo, which was in agreement with the previous results in vitro." (PMID 25974964, 2015). "Knockdown of endogenous RBP2 with specific small interference RNA dominantly inhibits GC cell proliferation in vitro and tumor development in vivo." (PMID 25015565, 2014). "An endothelial cell tube formation assay, VEGF enzyme-linked immunosorbent assay, real-time PCR and western blotting were performed to detect the potential mechanisms mediated by RBP2 in tumor angiogenesis." (PMID 25162518, 2014). "Taken together, these results suggest an oncogenic role for RBP2 in tumor angiogenesis and progression." (PMID 25162518, 2014). "The aim of this study is to detect the potential role of Retinoblastoma binding protein 2 (RBP2) in the tumor angiogenesis of non-small cell lung cancer (NSCLC)." (PMID 25162518, 2014). "More importantly, RBP2 is believed to participate in many cell biological functions, especially in tumor biology." (PMID 24376841, 2013). "Furthermore, genetic ablation of JARID1A/RBP2 decreased tumor formation in the pancreatic islets of Men1 (a tumor suppressor)-defective mice and in the pituitary glands of Rb(+/−) mice, thereby improving the survival of these mice." (PMID 31221981, 2019). "Taken together, our results support the hypothesis that the aberrant overexpression of RBP2 is a frequent contributing factor to tumor formation and metastasis in enteropancreatic NETs." (PMID 27548814, 2016). "This TGF-β1-(p-Smad3)-RBP2- E-cadherin-Smad3 feedback circuit may be a novel mechanism for GC malignant progression and suppression of RBP2 expression may serve as a new strategy for the prevention of tumor distant metastasis." (PMID 25974964, 2015).